CDKN1A (cyclin dependent kinase inhibitor 1A)
Diseases named in the same sentence as CDKN1A in open-access papers (continued):
Sharing a sentence is not in itself a finding about the gene and the disease.
tumor (continued). "However, only vesicles from C. paradisi could block the G2/M phase of tumor cells by enhancing gene expression of CDKN1A (encoding p21) and reducing levels of cyclin B1 and cyclin B2." (PMID 41278192, 2025). "Highly expressed CDKN1A may play a tumor suppressor role by encoding p21." (PMID 37608887, 2023). "Loss of SRC-1 expression dramatically increased tumor latency in this model, which correlated with decreased proliferation index and upregulation of cell cycle inhibitors such as transforming growth factor β2 (5.2 fold), Cdkn1a (8.8 fold), and Cdkn2b (8.5 fold)." (PMID 21080969, 2010). "The analysis identified miR‐93‐5p binding sites within the 3′‐UTRs of several key tumor‐associated genes, including PTEN, CDKN1A (p21), TP53INP1, and THBS2." (PMID 41159542, 2026). "Several hypoxia genes with high-frequency somatic mutations were identified, including CDKN1A, PPARGC1A, and AKAP12, which showed unequivocal associations with tumor initiation." (PMID 38806990, 2025). "In contrast, CDKN1A upregulation reinforced the cell cycle arrest observed in tumor cells, while FABP1 and BCL2A1 suggest metabolic and apoptotic adjustments in the post-knockdown state." (PMID 41411347, 2025). "RNA sequencing revealed upregulation of tumour suppressor genes, including CDKN1A and NR4A331,32, and downregulation of tumour-promoting genes, including CA9, EFNA1, and SUSD233–36." (PMID 41381717, 2025). "Conversely, NO also exhibited tumor-suppressive effects, including cell-cycle arrest, apoptosis induction, promotion of cancer stem-like cells, and upregulation of tumor suppressor genes like CDKN1A and RASSF1A." (PMID 40227440, 2025). "Study has shown that CDDP/PEM-induced upregulation of CDKN1A can induce cell cycle arrest and ferroptosis, thereby promoting tumor cell death." (PMID 40515824, 2025). "We observed significantly elevated UBR4 and reduced CDKN1A expression in human LUAD tumor tissues from clinical databases." (PMID 40531870, 2025). "Gene expression analyses in tumor tissues showed significantly increased mRNA levels of Cxcl10 and Cdkn1a in the combination treatment group, in line with the in vitro responses to CM272 in cultured PDAC cells." (PMID 39810240, 2025). "Asns (Unfolded protein gene), Vldlr and Cdkn1a (mTORC1 pathway) showed upregulation in GCP-like tumor cells in P16 SmoM2-Ptenfl/fl compared to P22 SmoM2 tumors." (PMID 40766638, 2025).
tumor (continued). "Mechanistically, G9a-mediated deposition of H3K9me1/2 represses tumor-suppressor genes such as CDKN1A/p21, E-cadherin, and PTEN, thereby promoting cell proliferation, epithelial-to-mesenchymal transition (EMT), and chemoresistance." (PMID 41419197, 2025). "Octreotide and pasireotide treatment increased CDKN1A/B (cell cycle-brakes) mRNA levels, which is consistent with reports in other tumour types reporting antiproliferative effects through the reduction of their respective proteins (p21 and p27)." (PMID 40268793, 2025). "For instance, EZH2’s dual role in suppressing tumor suppressor genes (e.g., CDKN1A, NLRP3) while activating pro-survival signals (e.g., Snail/EGFR) highlights its adaptability as a molecular switch in resistance trajectories." (PMID 40701777, 2025). "Mechanistically, the expression ofTWIST2 was found to activate the CDKN1A gene (cell cycle regulator) and repress the tumor-progressive genes, indicating its tumor-suppressive nature." (PMID 39941895, 2025). "In the HBx dysregulated HBV-HCC pathways, this panel of MIRNAs can influence a number of genes in the TGF-B/SMAD pathway by targeting validated gene targets like TGFBR1/SMAD3/, CDKN1A and MYC to influence both oncogenesis and the loss of tumor suppression." (PMID 38256049, 2024). "The results of tumor formation experiment in nude mice showed that overexpression of CDKN1A or treatment with STM2457 in cells with high POP1 expression greatly impaired the tumor formation ability." (PMID 39268503, 2024). "A previous study found that the emergence of cdkn1a's antisense DNA damage‐activated RNA promoter as a conspicuous presence in tumour tissues renders it a key protagonist, additionally serving as an independent harbinger of OS in ccRCC." (PMID 39011666, 2024). "Exposure to Eo33-EV, but not to Eo5-EV, up-regulated cyclin-dependent kinase inhibitor (CDKI) protein-related genes in tumor cells, specifically Cdkn1b and Cdkn2b in B16 cells and Cdkn2b and Cdkn1a in TC1 cells." (PMID 39061080, 2024). "Among those highly upregulated genes affected by RT in cell cycle and DNA replication pathways, Bax, Cdkn1a, and Aurkb were validated in qRT-PCR of these tumor samples." (PMID 39578426, 2024). "Conversely, PECAM1 and CDKN1A were upregulated in tumor tissues but downregulated in groups with higher TNM categories, advanced cancer stages, and grades." (PMID 38802480, 2024). "Profiling expression of Cdkn1a across the CD8 T cells in the tumor, we see that Cdkn1a is broadly upregulated across all T cell populations in the tumor (Fig. 4aiii), suggesting that these cells were present at the time of radiation." (PMID 38789721, 2024). "Accordingly, we found that the cell growth of tumor cells transfected with MRCP for CDKN1A was significantly inhibited, while the growth of normal cells was not significantly affected." (PMID 39507755, 2024). "KEGG pathway analysis indicates that the selected miRNA panel can specifically target SMAD3/CDKN1A/MYC in the TGF-B/SMAD pathway to influence tumor suppression and oncogenesis, as well as target CASP3 in the P13K/AKT pathway to influence apoptosis." (PMID 38256049, 2024). "Panobinostat exhibited a marked reduction in tumor growth, accompanied by inhibition of the cell cycle pathway and a decrease in cell cycle regulators like CDKN1A via in vitro cytotoxicity assays and in vivo xenograft models." (PMID 38994794, 2024).
tumor (continued). "It is worth noting that inducing CDKN1A expression or stability by a variety of methods has shown remarkable effects in inhibiting tumor progression and enhancing the therapeutic sensitivity of tumors." (PMID 39268503, 2024). "For example, combination treatment with HDAC inhibitor SAHA and DNMT inhibitor 5-Aza have resulted in significant delays in tumor growth in vivo by increasing expression of CDKN1A (or P21)." (PMID 38272889, 2024). "Specifically, CtBPs are involved in modulating genes implicated in tumor suppression and cell cycle progression, such as E-cadherin (also known as cadherin 1, CDH1), cyclin-dependent kinase inhibitor 1 A (CDKN1A), and CDKN2A." (PMID 38902802, 2024). "CDKN1A, known for its role in cell cycle regulation and tumor suppression, governs cell proliferation dynamics." (PMID 38812942, 2024). "It has been found that CDKN1A regulates DNA damage repair, which contributes to tumor radioresistance." (PMID 38468925, 2024). "Forced expression of CEACAM1 in thyroid cancer cells promoted cell–matrix adhesion, migration and tumor invasiveness via upregulation of cyclin dependent kinase inhibitor 1A (p21) and diminished retinoblastoma protein (Rb) phosphorylation." (PMID 38077351, 2023). "MiR-17-5p inhibits PTEN and CDKN1A (p21 gene), leading to tumor development through increased cell circulation, proliferation, and tumor metastasis." (PMID 37370750, 2023). "Sixty per cent of the tumours analysed displayed this signature of SRSF3‐miR‐17/20a‐CDKN1A expression." (PMID 37306233, 2023). "CDKN1A functions as a tumor suppressor by blocking cell cycle progression via inhibiting CDK1 and CDK2, and CDKN1A-deficiency promotes spontaneous and induced tumors in different tissues." (PMID 36765862, 2023). "The upstream regulator analysis of cisplatin revealed an increase in FAS, BTG2, SESN1, and CDKN1A, and the involvement of the tumor microenvironment pathway." (PMID 38003016, 2023). "ATBF1, encoded by ZFHX3, negatively regulates AFP and MYB, positively regulates CDKN1A expression, and has been reported as a tumour suppressor gene in other types of cancer." (PMID 38104198, 2023). "It is well known that low expression of CD81 has more metastatic potential in HCC cell lines and the CDKN1A suppression facilitates cell cycle progression from the G1 to the S phase to promote tumor cell proliferation." (PMID 37051592, 2023). "The SRSF3‐miR‐17/20a‐CDKN1A “signature” was sufficient to classify patients with poorly differentiated tumours." (PMID 37306233, 2023). "CDKN1A is one of the key molecules involved in cell cycle progression and was first identified as a tumour suppressor." (PMID 36765397, 2023). "We also investigated gene expression in these tumours and observed a senescence signature including an up-regulation of CDKN1A (P21) specific to DMG_K27-MAPK which is usually more present in paediatric LGGs." (PMID 38066305, 2023). "The expression level of CDKN1A is up-regulated, which can effectively weaken the promoting effect of miR-300 on tumor growth (about 2 mm)." (PMID 38070141, 2023). "Initial reports highlighted BMP7’s ability to curtail tumor growth by upregulating CDKN1A in prostate cancers." (PMID 38049682, 2023). "Complicating matters further, the expression of CDKN1A/p21 is elevated in certain tumour types while downregulated in others." (PMID 38139316, 2023). "The cyclin-dependent kinase inhibitor 1 A (CDKN1A), also named p21cip1/waf1, is a well-studied tumor suppressor, known for mediating cell cycle arrest." (PMID 37012388, 2023).
tumor (continued). "More recently, the Cdkn1aSUPER mouse is shown to be more resistant to transformation and exhibit a strong cancer protection phenotype, establishing a direct gene dosage-dependent tumor suppressor function for CDKN1A." (PMID 35401501, 2022). "Recent studies have shown that the downregulation of miR-106b by grape seed procyanidin (GSE) induced the expression levels of tumor inhibition cycle-independent kinase inhibitor 1A (CDKN1A) and p21, which further promotes the antitumor effect of GSE." (PMID 36144639, 2022). "Transcriptomic analysis showed LY500307 increased expression of tumor suppressor genes such as CDKN1A and FDXR." (PMID 35806169, 2022). "Genetic disruption of SLFN11 stimulated expression of NFκB target genes, including CDKN1A (p21) and significantly delayed tumor growth and improved survival in a GBM orthotopic patient-derived xenograft (PDX) mouse model." (PMID 36382088, 2022). "Here, we demonstrate that tumor cell phagocytosis drives the pro-inflammatory activation of TAMs and identify a key role for the cyclin-dependent kinase inhibitor CDKN1A (p21)." (PMID 36347876, 2022). "Increased expression of p21 serves as a cellular defense mechanism for suppressing further chromosomal instability and tumor development, and reduced expression following CDKN1A knockout leads to chromosomal instability." (PMID 35064135, 2022). "FOXOs are discovered as a tumor suppressor through activating G2/M arrest related genes CDKN1A and GADD45A, apoptosis related genes FAS, DR4 and DR5, respectively 58-62." (PMID 35813464, 2022). "At last, rescue experiments proved the anti-tumor effect of inhibition of MSTO2P was partially recovered due to the knockdown of CDKN1A in HT-29 cells." (PMID 35346226, 2022). "The further analysis showed CDKN1A had a similar result with miR-642a-3p based on different T stages, which represented tumor invasion." (PMID 35484565, 2022). "CDKN1A (P21) is a member of cyclin-dependent kinase inhibitors and it has been regarded as a tumor suppressor by regulating the cell cycle and maintaining genomic stability." (PMID 35123499, 2022). "According to the obtained results, EHMT1 was significantly related to apoptosis and the cell cycle process and had an important impact on regulating the apoptosis and cell cycle of tumor cells by regulating the expression of CDKN1A." (PMID 36092868, 2022). "Inactivating mutations in other pro-senescence mediators like CDKN1A, associated with bladder cancer, or RB1, linked to retinoblastoma, provide further evidence of the anti-tumour role of senescence." (PMID 33439271, 2021). "Studies have shown that TRIM71 can inhibit the expression of tumor suppressor CDKN1A/p21 and promote the proliferation of tumor cells." (PMID 33854615, 2021).
tumor (continued). "Of note, our results showed that ATP5MC3, CDKN1A, and SLC7A11 expression was dramatically positively related with the tumor mutational burden (TMB) score in EC." (PMID 34531924, 2021). "Cdkn1A is a cell cycle-related gene located on chromosome 6, and as a tumor suppressor gene, it is widely and expressed at low levels in tumors." (PMID 34987399, 2021). "In an opposite manner, Akt-activated CDKN1A was found to accelerate tumor onset and promote lung metastasis in vivo." (PMID 33621203, 2021). "It has become increasingly clear that CDKN1A can function as an oncogene or as a classic tumor suppressor." (PMID 33621203, 2021). "In this study, the correlation between CDKN1A and the immune system was assessed with the TISIDB database, and the results revealed that CDKN1A had the highest correlation with tumor-infiltrating lymphocytes including Tcm_CD4, pDC, Act_DC and Th1." (PMID 33621203, 2021). "Increased proliferation in tumor cells frequently correlates with reduced expression levels of cyclin-dependent kinase inhibitors, including CDKN1A." (PMID 33731112, 2021). "In other words, mean CTNNB1 mRNA expression was lower in the tumour subset with high CDKN1A expression than in the tumour subset with low CDKN1A expression, which was consistent with β-catenin having an inhibitory effect on CDKN1A mRNA expression." (PMID 34389725, 2021). "Previous reports have shown that the tumour suppressor isoform of ZFHX3 (isoform P1) upregulates the expression of the tumour suppressor CDKN1A and downregulates the expression of the oncogene MYB." (PMID 33499898, 2021). "CDKN1A appears to exhibit dual-role behavior and acts either as an oncogene or tumor suppressor depending on the cell types or cellular localization." (PMID 33621203, 2021). "Compelling evidence has demonstrated that DUSP5 and CDKN1A are key tumour suppressors in various cancers, mediating cell cycle and malignant progress." (PMID 33145887, 2021). "Take the case of cyclin-dependent kinase inhibitor 1 (CDKN1A), or p21Cip1, a cell cycle regulator and tumor suppressor, overexpressed in both LNCaPR and C4-2BR." (PMID 33799432, 2021). "Such as LncRNA AB074169 functions as a tumour suppressor during PTC tumorigenesis via modulation of KHSRP‐mediated CDKN1a expression." (PMID 34337858, 2021). "CDKN1A, acts as a tumor suppressor in many cancers, where we found that CDKN1A is a downstream regulator of AGAP2-AS1-mediated CCA cell growth arrest." (PMID 33522895, 2021). "CDKN1A is not only a tumor suppressor, a cell cycle inhibitor, and a senescence inducer but also a key regulator of cell migration, apoptosis, differentiation, DNA repair, and transcription." (PMID 34195287, 2021). "To answer this question we looked at the expression of genes involved in tumor resistance and identified CDKN1A as a gene overexpressed in both TSC2−/− AML organoids and kidney AML compared to control organoids and to normal kidney." (PMID 34764250, 2021). "The CDKN1A (p21), acts as the regulator of G1/S and G2 check points, has been found as a tumour suppressor in many types of cancer." (PMID 34164906, 2021). "Decreased expression of CDKN1A facilitates cell cycle progression from the G1 to S phase, thus promoting tumor cell proliferation." (PMID 34299042, 2021).